PERP (p53 apoptosis effector related to PMP22)
Diseases named in the same sentence as PERP in open-access papers (continued):
Sharing a sentence is not in itself a finding about the gene and the disease.
tumor (continued). "The elevated Akt expression observed in our study lends support to the hypothesis that Akt promotes tumor progression through increased cellular survival and proliferation, in opposition to the pro-apoptotic mode of action of PERP." (PMID 39201982, 2024). "Restoration of PERP function or enhancement of its expression could restore apoptotic mechanisms and suppress tumor growth." (PMID 39201982, 2024). "At present, a tumor-suppressive role of PERP has been confirmed in various cancers." (PMID 35936737, 2022). "Importantly, these insights suggest that keratinocytic differentiation markers, such as PERP, could serve as prognostic indicators of tumor behavior, while therapeutic strategies targeting p63-mediated pathways may offer novel avenues to mitigate MCC plasticity and treatment resistance." (PMID 41131107, 2025). "GHRL, KLF4, and DUSP5 expression levels were relatively lower in tumor tissues, whereas DSP, PERP, and MMP9 were highly expressed in tumor tissues." (PMID 38273348, 2024). "Anti-PERP immunostaining revealed light to minimal staining in tumor-adjacent tissue, intense staining of primary PDAC lesions, and diffuse PERP reactivity in metastatic tissues." (PMID 34874916, 2022). "Among these DEGs several genes with oncogenic and/or metastasis promoting function (e.g. STC1, YES1, PORCN) were found to be down-regulated and certain tumour suppressor genes (e.g. DKK1, PERP) showed overexpression in LINC00152-silenced cells." (PMID 32307642, 2020). "Our working model suggests that TRPS1 recruits USP4 to stabilize HDAC2 repressing the expression of AES, Casp7, PERP, and ZW10 to confer tumor growth." (PMID 30071870, 2018). "These scenarios fit well with our working model that TRPS1 recruits USP4 to stabilize HDAC2 and represses expression of AES, Casp7, PERP, and ZW10 to confer tumor growth." (PMID 30071870, 2018). "Our identification here of the MDA-7/IL-24 target PERP, another member of the GAS-3/PMP-22 family with strong tumor inhibitory activity, further highlights the importance of this gene family in malignant transformation." (PMID 26460950, 2015). "Mechanistically, MDA-7/IL-24 exerted its tumor suppression effect on HER2+ breast cancer cells, at least in part, through PERP, a member of PMP-22 family with growth arrest and apoptosis-inducing capacity." (PMID 26460950, 2015). "It is, therefore, proposed that the diminished tumor development observed in the absence of PERP may be explained by impaired adhesion due to aberrant desmosome assembly." (PMID 39201982, 2024).
infection (3 papers, 2011 to 2019). The state of being infected such as from the introduction of a foreign agent such as serum, vaccine, antigenic substance or organism. "We therefore propose that the upregulation of autophagy following infection promotes the stabilization of PERP at the PM." (PMID 31508245, 2019). "We found a significant increase after 1 h post-infection (MOI = 10) in the number of SE MY1WT infecting PERP-overexpressing dGCs compared with that of control dGCs (P < 0.01)." (PMID 31565575, 2019). "When PERP knockdown followed by treatment with MY1WT in dGCs, there is an opposite trend emerged of the mRNA expression level of TNF-α (P <0.05), however, overexpression of PERP or knockdown PERP showed no significant mRNA level change of IL-6, IL-1β, TNF-α, and IFN-γ during MY1ΔsipC infection." (PMID 31565575, 2019).
benign tumors (1 paper, 2024). "The differences in expression between precancerous and benign tumors provide further evidence of a role for PERP and Akt in the transition from benign to malignant states." (PMID 39201982, 2024). "The differences in expression between precancerous and benign tumors provide further evidence of the role of PERP and Akt in the transition from benign to malignant states." (PMID 39201982, 2024). "Additionally, the significant expression differences between precancerous and benign tumors indicate a potential role for PERP and Akt in the progression from benign to malignant states." (PMID 39201982, 2024). "Furthermore, significant differences were observed between PERP and Akt positive expression in precancerous (72.8% vs. 37.7%) and benign tumors (26.6% vs. 0.9%) (p = 0.001 for both comparisons)." (PMID 39201982, 2024).
PERP also shares sentences with these, for which no sentence is quoted: head and neck carcinoma (1 paper); hepatoma (1); Hyperkeratosis (1); ichthyosis (1); Infertility (1); nasopharyngeal carcinoma (1); neurodegenerative disease (1); Obesity (1); osteosarcoma (1); psoriasis (1); rheumatoid arthritis (1).